SCRT2 (scratch family transcriptional repressor 2)
Description:
May be involved in transcriptional regulation.
Synonyms: ZNF898B
Tractability: No criterion of Open Targets' tractability assessment is met for any kind of drug.
Gene: Protein-coding gene on chromosome 20 (661,596 to 675,802, reverse strand). Ensembl gene ENSG00000215397.
Subcellular location: Nucleus
Subcellular location (Human Protein Atlas): Nucleoplasm
Gene Ontology:
Molecular function: sequence-specific double-stranded DNA binding; DNA-binding transcription factor activity, RNA polymerase II-specific; DNA-binding transcription repressor activity, RNA polymerase II-specific; E-box binding; RNA polymerase II cis-regulatory region sequence-specific DNA binding
Biological process: negative regulation of extrinsic apoptotic signaling pathway via death domain receptors; negative regulation of transcription by RNA polymerase II; regulation of DNA-templated transcription
Cellular component: chromatin; nucleus
Genetic constraint (gnomAD): Loss-of-function variants: 2 observed, 0.86 expected, observed/expected ratio (o/e) 2.34. That is too few expected variants to judge how well the gene tolerates losing a copy. Missense variants: 417 observed, 304.73 expected, observed/expected ratio (o/e) 1.37, 90% interval 1.26 to 1.48. Synonymous variants: 230 observed, 148.57 expected, observed/expected ratio (o/e) 1.55, 90% interval 1.39 to 1.73.
Homologues: Orthologues: macaque SCRT2 (99% identical), chimpanzee SCRT2 (98% identical), dog SCRT2 (97% identical), pig SCRT2 (96% identical), mouse Scrt2 (92% identical), guinea pig SCRT2 (81% identical), rat Scrt2 (81% identical), tropical clawed frog scrt2 (62% identical), zebrafish scrt2 (57% identical), Drosophila melanogaster scrt (53% identical), Drosophila melanogaster CG12605 (48% identical), Drosophila melanogaster Kah (37% identical), and 2 more. Paralogues in human: SCRT1 (64% identical), SNAI2 (35% identical), SNAI3 (34% identical), SNAI1 (30% identical), HIC1 (22% identical), PRDM1 (21% identical), ZNF410 (21% identical), HIC2 (21% identical), MTF1 (21% identical), PRDM10 (20% identical), ZBTB16 (20% identical), PATZ1 (20% identical), and 24 more.
Diseases named in the same sentence as SCRT2 in open-access papers:
SCRT2 is named in the same sentence as 3 diseases in open-access papers, as found by Europe PMC text mining. Sharing a sentence is not in itself a finding about the gene and the disease. The quoted sentences say what the papers report.
depression (1 paper, 2021). "The common DEGs of depression and NASH have four TFs, i.e., ATF, SRF, SREBF1, SCRT2." (PMID 34833079, 2021).
glioma (1 paper, 2023). A benign or malignant brain and spinal cord tumor that arises from glial cells (astrocytes, oligodendrocytes, ependymal cells). "However, we found 240 TFBS that were present in the promoters of genes overexpressed in GIV gliomas, and this set included binding sites for c-Jun, SCRT2, PITX3, ERR1, or ZN784." (PMID 36850002, 2023).
SCRT2 also shares sentences with these, for which no sentence is quoted: cardiovascular disease (1 paper).